HTRA1 (HtrA serine peptidase 1)
Diseases named in the same sentence as HTRA1 in open-access papers (continued):
Sharing a sentence is not in itself a finding about the gene and the disease.
tumor (continued). "Recent study where inhibition of HTRA1 in the tumor stroma impaired tumor progression by deregulating angiogenesis, is in favor of HTRA1 acting as an oncogene and in concordance with our findings." (PMID 37834386, 2023). "The expression of HTRA1 is downregulated in a variety of tumours, such as ovarian tumours, thyroid tumours and non-small cell lung tumours, which activates the TGF-β signalling pathway to promote tumour cell proliferation." (PMID 36430917, 2022). "Consistent with the concept that HtrA1 is a tumor suppressor, HtrA1 expression downregulation in SKOV3 cells after antisense transfection enhanced anchored independent growth." (PMID 34563186, 2021). "HtrA1, which is a tumor suppressor, mediates the proliferation, migration, and invasion of cancer cells via a series of signals in the tumor progression and the microenvironment." (PMID 34563186, 2021). "HTRA1 has been suggested to participate in chemotherapy-induced cytotoxicity and has been proposed to be a tumor suppressor." (PMID 34202399, 2021). "The difference is that HTRA3 mRNA levels gradually decline as tumor grade increases, while HTRA1 mRNA levels immediately decrease with the increase in early G1EC, then remain at a lower level, and then dynamic change with the increase in tumor grade." (PMID 34563186, 2021). "Patients with higher HtrA1 expression levels showed a higher tumor response rate to chemotherapy than patients with lower expression levels." (PMID 34563186, 2021). "Inhibition of HTRA1 expression induces tumor stem cell characteristics in samples and CDDP resistance through the PI3K/Akt signal pathway." (PMID 34563186, 2021). "The levels of HtrA1 and HtrA2 proteins were reduced in tumor tissue when compared to unchanged mucosa, specifically in primary lesions of metastasizing disease." (PMID 32486357, 2020). "In cancers, HTRA1 regulates a broad range of signalling in tumour microenvironment, and through which mediates cancer cell proliferation, migration and invasion." (PMID 31867863, 2020). "Compared with the vehicle control group, the knockdown of HtrA1 in NCI-H460 cells resulted in a significant increase in tumor growth." (PMID 32878625, 2020). "In the case of several cancers (e.g., ovarian, gastric and breast tumors), a diminished level of HtrA1 protein in tumor tissue has been correlated with poor response to platinum-based chemotherapy, metastasis, and worse clinical outcome." (PMID 32486357, 2020). "In this study, we identified HtrA1 as a tumor suppressor gene that was involved in cancer cell proliferation and migration, and in CDDP resistance in NSCLC cells." (PMID 32878625, 2020). "This is evidenced on a functional level as systemic changes in HtrA-1 in murine tumor models lead to aberrancy of tumor vascularization." (PMID 33281553, 2020). "Functional studies indicate that HtrA1 regulates a number of signaling pathways and protein substrates that mediate anti-tumor efficacy." (PMID 32878625, 2020). "Surprisingly, the HtrA1 protein levels in both tumor tissue groups were slightly reduced and they reached significance in primary tumors of metastasizing disease." (PMID 32486357, 2020). "In NSCLC, the downregulation of HtrA1 mRNA and protein levels increases the number of tumor stem cell phenotypes in CDDP-resistant cells." (PMID 32878625, 2020). "In the present study, a meta-analysis was conducted to assess the potential role of HtrA1 as a tumor marker and/or prognostic factor in a number of tumors." (PMID 29409460, 2018). "In a previous review, our group explored the potential role of HtrA1 as a tumor marker and/or prognostic factor." (PMID 29409460, 2018). "Most current studies focus on the role of HtrA1 in tumor development and progression through analysis of its expression as mRNA or protein, probably because proteins are more varied than DNA or RNA and therefore carry more information than nucleic acids." (PMID 29409460, 2018).
tumor (continued). "HTRA1 down-regulation is highly important in cancer progression and in acquiring aggressive tumor traits, mainly due to the elimination of its tumors pro-apoptotic and anti-growth properties." (PMID 29269789, 2017). "In the current study, we show that, in accordance with its tumor suppressive activity, HTRA1 acts as an inhibitor of the canonical Wnt cascade by down-regulating the Wnt signal and the expression of specific Wnt target genes." (PMID 29269789, 2017). "In the present study, we show that in accordance with its tumor suppressor traits, HTRA1 reduces the oncogenic Wnt signal, the β-catenin expression levels, and the proliferative abilities of cells." (PMID 29269789, 2017). "Exogenous HTRA1 expression induces apoptosis and a reduction of cell proliferation in transformed cells, suggesting a tumor suppressor role for this protein." (PMID 27809811, 2016). "This manuscript reviews the current cancer-related HtrA1 research from the methodological and clinical standpoints including studies regarding its potential role as a tumor marker and/or prognostic factor." (PMID 26035313, 2015). "Additional studies are therefore required to clarify the role of HtrA1 in the growth of normal and tumor tissue cells." (PMID 26035313, 2015). "Its aim was to test the value of HtrA1 as a new biomarker of tumor differentiation and aggressiveness by quantifying its expression and localization in NB." (PMID 26035313, 2015). "The present manuscript reviews current cancer-related HtrA1 research from the methodological and clinical standpoints and studies exploring the potential role of HtrA1 as a tumor marker and/or prognostic factor in a number of tumors." (PMID 26035313, 2015). "In the breast, HTRA1 expression is prominent in normal ductal glands, whereas its expression is distinctly reduced or even lost in tumor tissues of patients with ductal carcinoma in situ (DCIS) or invasive breast carcinoma." (PMID 23580433, 2013). "In the multivariable model including tumor stage and adjuvant treatment, HTRA1 expression was confirmed as a clinically relevant parameter predicting OS or DFS." (PMID 23580433, 2013). "Relevant promoter methylation was detected only in two out of the 12 tumor specimens, exhibiting low relative HTRA1 expression levels of 2.5 and 2.7, and in the MCF-7 cell line." (PMID 23580433, 2013). "Due to its ability to attenuate cell motility, growth and invasiveness, HTRA1 is also thought to act as a tumor suppressor." (PMID 23580433, 2013). "With respect to an optimized cut-off value of ≥48, deduced by means of the program R, 56 (43%) tumor specimens showed high HTRA1 expression and 75 (57%) low expression." (PMID 23580433, 2013). "Therefore, remote tumor-derived sEVs carrying HTRA1 strongly upregulated MMP-13 in OPs, significantly disrupting the bone marrow ecosystem." (PMID 40103824, 2025). "There was a statistically significant difference between the tumor samples and healthy controls, with a consistent finding of this work, that HtrA1 levels are higher in healthy controls or normal-looking tissue than in diseased tissue from patients with a variety of tumors." (PMID 38372785, 2024). "It is also reported that HTRA1 could participate intracellularly in cell apoptosis, migration, and invasion in tumor cells through EGFR pathways." (PMID 38334007, 2024). "Finally, HtrA serine peptidase 1 (HTRA1) on tumor-derived vesicles has been reported to upregulate MMP13 in osteoprogenitors which subsequently induce CD41- GMP clustering and systemic accumulation of protumoral Neu." (PMID 39148724, 2024). "On the other hand, HTRA1 is widely regarded as a tumor suppressor." (PMID 38334007, 2024). "In summary, the role of HTRA1 as an oncogene or tumor suppressor might be dependent on cellular context." (PMID 38334007, 2024).
tumor (continued). "In addition to serving as a tumor marker and/or prognostic factor, HTRA1 is also connected to tumorigenesis via regulating tumor cell proliferation, migration, apoptosis and differentiation." (PMID 38287020, 2024). "Overall, more work is needed to establish the role of HTRA1 in cancer in terms of whether it functions as an oncogene or a tumor suppressor." (PMID 37834386, 2023). "HTRA1 (high-temperature requirement protein 1) has been considered a tumor suppressor." (PMID 36992411, 2023). "Expression of HtrA proteins is associated with tumour initiation and the induction of IDO1 reported here may contribute to these actions, a result which may be linked to the induction of HtrA1 by TGF-β, a prominent inducer of IDO expression." (PMID 35371018, 2022). "Additionally, the methylation status of the HTRA1 catalyst is a biomarker concerning tumor cells or cells to be transformed." (PMID 34563186, 2021). "HtrA1 gene expression is decreased in diverse cancers, and it may play a role as a tumor suppressor for promoting the death of tumor cells." (PMID 34563186, 2021). "In the high-M group, many tumor suppressive genes were methylated and suppressed, but only three genes (KLF4, CACNB2 and HTRA1) seemed to be able to identify high-risk cases, while abnormal DNA methylation seemed to play a role in influencing important biological pathways." (PMID 34563186, 2021). "Notch-1 overexpression further reverses the inhibitory effect of HtrA1 on tumor cell growth." (PMID 34563186, 2021). "HtrA1 expression in tumor tissues is downregulated than that in adjacent liver tissues." (PMID 34563186, 2021). "HTRA1 is significantly expressed within the normal ductal glands in the breast, but HTRA1 expression is significantly downregulated or disappears within the tumor tissues of those with invasive BC or ductal carcinoma in situ (DCIS)." (PMID 34563186, 2021). "The role of HTRA1 in cancer has been defined as both tumour suppressive and pro-oncogenic." (PMID 33167358, 2020). "The expression of the HTRA1/2 genes diminished as the microsatellite instability of tumor advanced." (PMID 32486357, 2020). "The HTRA (high temperature requirement A) proteases promote apoptosis, may function as tumor suppressors and HTRA1 is known to be released by mast cells." (PMID 32560402, 2020). "Finally, our in vivo xenograft data indicated knockdown of HtrA1 in NCI-H460 cells resulted in a significant increase in tumor growth." (PMID 32878625, 2020). "Several lines of evidence exist showing that HtrA1 acts as a tumor suppressor." (PMID 32486357, 2020). "Interestingly, a previous study identified HTRA1 expression in the tumour stroma to regulate Notch signalling, thereby coordinating angiogenesis and enhancing tumour progression." (PMID 33167358, 2020). "The high similarity of the HtrA4 protein domain structure to that of HtrA1 and HtrA3 and implication of HtrA4 in oncogenesis suggested that it may function similarly to the HtrA1/3, which act as tumor suppressors and promote cell death." (PMID 31546993, 2019). "HTRA1 contributes to the tumor formation by inhibiting the TGF-beta pathway." (PMID 31001321, 2019). "The present data may provide a contribution to future work directed at exploring the role of HtrA1 in tumor development and progression and at establishing whether it may be used as a promising tissue marker for some tumors." (PMID 29409460, 2018). "Moreover, we found that overexpression of HtrA1 promoted apoptosis and suppressed the migratory ability of tumor cells." (PMID 30484491, 2018). "The present data may provide a contribution to future research work directed at exploring the role of HtrA1 in tumor development and progression and at establishing whether it may become a promising tissue marker for some tumors." (PMID 29409460, 2018). "Indeed, several lines of evidence indicate that HtrA1 functions as a tumor suppressor in various solid tumors, such as ovarian and lung cancer and mesothelioma." (PMID 29409460, 2018).
tumor (continued). "Moreover, results showed that overexpression of HtrA1 promoted the apoptosis and suppressed the migratory ability of tumor cells." (PMID 30484491, 2018). "An important finding of the study was that, in the absence of significant statistical heterogeneity, there was a statistically significant difference between the tumor samples analyzed and HC and NL tissue specimens; this applied both to HtrA1 measured as mRNA and as protein." (PMID 29409460, 2018). "Immunostaining of HtrA1 was observed both in the cytoplasm and in the nuclei of tumor cells." (PMID 30131069, 2018). "Overexpression of HtrA1 promoted apoptosis and suppressed migratory ability of tumor cells." (PMID 30484491, 2018). "Additionally, a reduced proliferation of tumour cells and a decreased tumour growth have been observed upon HTRA1 overexpression." (PMID 28326227, 2017). "Numerous experimental findings suggest a tumour suppressor function for HTRA1." (PMID 28326227, 2017). "The authors found that HtrA1 was underexpressed in metastases compared with the primary tumor." (PMID 26035313, 2015). "In these tumors, absence of HTRA1 expression has also been associated with more aggressive tumor phenotypes and higher grading." (PMID 23580433, 2013). "Comparison of the expression data between patient groups defined by clinical and histomorphological parameters revealed a statistical significant difference only for pT categories, indicating a decrease in HTRA1 mRNA levels with increasing tumor stage (p = 0.025)." (PMID 23580433, 2013). "Collectively, these results suggest that HtrA1 may function as a tumor suppressor by controlling the epithelial-to-mesenchymal transition, and may function in chemotherapeutic responsiveness by mediating DNA damage response pathways." (PMID 22761798, 2012). "Notably, HTRA1 from remote tumor-released sEVs was delivered to OPs in the bone marrow, and promoted the upregulation of matrix metalloproteinase 13 (MMP-13) in OPs, thus leading to the dislocation of hematopoietic stem cells and aggregation of CD41− granulocyte-monocyte progenitors (GMPs)." (PMID 40103824, 2025). "Hence, HTRA1 obtains a bi-directional regulation potential in different tumor cells." (PMID 38740771, 2024). "This suggested high HTRA1 expression might be correlated with suppressed anti‐tumor immunity." (PMID 38334007, 2024). "HtrA1 has already been hypothesized to function as a tumour suppressor." (PMID 38609535, 2024). "Promoter methylation-mediated HtrA1 downregulation induces diverse phenotypes that may serve as cancer cell hallmarks; therefore, HtrA1 may be used as a biomarker for malignant transformation or tumor development." (PMID 34563186, 2021). "HtrA1 has been reported to regulate such processes through modulation of growth factor systems, like the system mediated by the extracellular protein transforming growth factor β (TGF-β) as demonstrated by the association of its expression with specific tumor behaviors." (PMID 29409460, 2018). "Finally, according to recent evidence HtrA1 downregulation induces the acquisition of phenotypes such as increased proliferation, delayed onset of senescence, altered centrosome number and positioning and polyploidy, all hallmarks of tumor cells." (PMID 29409460, 2018). "On the basis of our data, we propose a model whereby LOX activates the secreted protease HTRA1, which inhibits TGFβ1 signalling, causing increased expression of the EGF-like domain containing protein MATN2, which then enhances EGFR signalling to drive tumour growth and metastasis." (PMID 28416796, 2017). "Furthermore, several publications link HTRA1 to tumorigenesis as its gene has been found to be downregulated in many tumours, and forcing its re-expression interfered with proliferation of metastatic melanoma cells and cell migration, suggesting a tumour suppressor function." (PMID 27388476, 2016). "We suggest that HtrA1 may represent another tumor suppressor in this group." (PMID 22761798, 2012).
tumor (continued). "A number of studies have suggested that HtrA1 may function as a tumor suppressor." (PMID 22761798, 2012). "The expression levels of HtrA1-4 in HNSCC and non-tumor cells were also measured by RT-PCR and western blot verification." (PMID 37842043, 2023). "CPTP was found to be involved in pyroptosis, and while its pro-tumor function in DLBCL was discovered in our study, HTRA1, RBBP7, NFE2L2 and SCAF11 were found to be tumor suppressive." (PMID 36551263, 2022). "The human HTRA1 gene is located on chromosome 10q25.3-q26.2, which is very close to DMBT1, suggesting HtrA1 as a presumed tumor suppressor." (PMID 34563186, 2021). "Western blot data also indicated that the increased the expression of HtrA1 by up-regulating the level of acetylated Histone4 in SAHA/bexarotene/CDDP and DW22/CDDP treated NCI-H460/CDDP tumor tissues." (PMID 32878625, 2020). "HtrA1 generally acts as an inhibitor of TGF-β signaling, which has a suppressive role at early steps of colorectal transformation, but promotes tumor progression at late stages." (PMID 32486357, 2020). "The best-studied members of this protein family in humans are HTRA1 and HTRA2 that are both involved in tumour suppression and in the control of proliferation, migration, and neurodegeneration." (PMID 28326227, 2017). "As was consistent with the qRT-PCR results, SPP1, COL1A1 and NT5E proteins were up-regulated, while the expression of HTRA1 and ANGPT1 were down-regulated in the tumor compared with ANPT groups (n = 29)." (PMID 27690016, 2016). "Besides, HTRA1 knockdown inhibited the growth of xenografts derived from orthotopic implantation of GBM cells and prolonged the survival time of tumor‐bearing mice." (PMID 38334007, 2024). "Thirdly, since parameters such as histological type and tumor grade and stage have not been addressed in all the studies, it is impossible to establish how HtrA1 expression varies in relation to these factors." (PMID 29409460, 2018). "We selected five genes, SPP1, COL1A1, NT5E, HTRA1 and ANGPT1, of 15 genes whose coding proteins could be secreted from the pituitary, and we examined their tumor expression in 118 CD patients." (PMID 27690016, 2016). "The authors found an association between HtrA1 level and TNM stage, but not between tumor differentiation, gender or age." (PMID 26035313, 2015). "The current literature does not, therefore, provide conclusive data on the role of HtrA1 as a tumor marker, but documents the need for further research." (PMID 26035313, 2015). "HtrA1 levels correlated with Edmondson and Steiner’s criteria and vascular invasion (P=0.014) but not with gender, age, tumor size or presence of metastases." (PMID 26035313, 2015). "HTRA1 is a member of the HTRA (High-Temperature Requirement Factor A) family of serine proteases and plays a protective role in various malignancies due to its tumor suppressive properties." (PMID 24643221, 2014). "Despite these correlations, the tumor suppressor function(s) of HtrA1 has not yet been definitively tested or proven in animal models." (PMID 22761798, 2012). "However, there are also some different voices that current research on HTRA1 does not conclusively support its role as a tumor suppressor." (PMID 38287020, 2024). "However, recent studies mainly focus on the effects of HTRA1 on tumor progression, and its functional mechanism in CRC has not been clarified yet." (PMID 38740771, 2024). "The current HtrA1 research does not conclusively support its role as a tumor suppressor." (PMID 26035313, 2015). "Current research on HtrA1 does not conclusively support its role as a tumor suppressor." (PMID 26035313, 2015). "Moreover, HTRA1 expression was maintained as a statistically significant factor which predicted outcome (DFS) independent from nodal status when tested among the established clinical factors age, tumor stage, nodal involvement and nuclear grading (binary variables) in the multivariable analysis." (PMID 23580433, 2013).
tumor (continued). "HTRA1 overexpression prevents cell proliferation in the HPV-negative cell line, as described in the literature in other tumor cells, via cell cycle arrest in G0/G1." (PMID 27809811, 2016).